COL4A1 (collagen type IV alpha 1 chain)
Diseases named in the same sentence as COL4A1 in open-access papers (continued):
Sharing a sentence is not in itself a finding about the gene and the disease.
nasopharyngeal carcinoma (2 papers, 2010). A carcinoma arising from the nasopharyngeal epithelium. "The literature reported that the in nasopharyngeal carcinomas underexpressed hsa-mir-29c (expression fold change (tumor/normal)=0.20) target overexpressed gene COL4A1(expression fold change(tumor/normal)=5.24)." (PMID 21143783, 2010). "Mir-29c was reported to be under expressed in nasopharyngeal carcinomas and up regulated genes COL4A1, COL4A2 and TDG." (PMID 21114830, 2010).
osteoporosis (2 papers, 2005 to 2020). A condition of reduced bone mass, with decreased cortical thickness and a decrease in the number and size of the trabeculae of cancellous bone (but normal chemical composition), resulting in increased fracture incidence. "Our result indicated that PRKCZ, GAN11 and COL4A1 may be associated with the development of osteoporosis in postmenopausal women." (PMID 32496000, 2020). "By searching for references in PubMed we discovered that 9 of these genes (~ 15% of the total) are already candidates for involvement in diseases including Alzheimers (ABCA2), osteoporosis (COL4A1 and COL4A2) and schizophrenia (SLIT3)." (PMID 15766383, 2005). "COL4A1 is up‐regulated in bone tissue of patients with osteoporosis." (PMID 32496000, 2020).
Parkinson disease (2 papers, 2016 to 2022). A progressive degenerative disorder of the central nervous system characterized by loss of dopamine producing neurons in the substantia nigra and the presence of Lewy bodies in the substantia nigra and locus coeruleus. "Future studies may address the investigation of col4a1 and col25a1 protein distribution and molecular pathways to generate Alzheimer’s or Parkinson’s disease models." (PMID 35163698, 2022).
peripheral artery disease (2 papers, 2021). "Interestingly, the COL4A1/A2 locus encoding the ⍺1- and ⍺2-chains of collagen type IV (which comprise the scaffold of the arterial BM) is a highly replicated genome-wide association study (GWAS) hit for coronary- and peripheral artery disease." (PMID 34496837, 2021).
periventricular leukomalacia (2 papers, 2021 to 2024). Periventricular leukomalacia (PVL) is a brain injury disorder characterized by the death of the white matter of the brain due to softening of the brain tissue. "Periventricular leukomalacia (PVL), defined as pre- or perinatal, post-hypoxic-ischemic leukoencephalopathy without porencephaly is reported in COL4A1 mutations." (PMID 37847489, 2024).
Pontine Autosomal Dominant Microangiopathy with Leukoencephalopathy (2 papers, 2019 to 2023). "First, it shows the co-segregation of a COL4A1 3’UTR variant with the disease in the family for which the name Pontine Autosomal Dominant Microangiopathy with Leukoencephalopathy (PADMAL) was coined." (PMID 36786861, 2023).
prostate carcinoma (2 papers, 2014 to 2017). A carcinoma that arises from epithelial cells of the prostate gland. "We found that depending on age of prostate cancer patients and Gleason score EMT genes with distinctly altered expression are: KRT18, KRT19, MUC1 and COL4A1, CTNNB1, SNAI2, ZEB1 and MMP3." (PMID 29206234, 2017).
pterygium (2 papers, 2019 to 2021). A wedge-shaped fibrovascular lesion arising from the bulbar conjunctiva and extending to the cornea. "It indicated miR-29b-3p might be implicated in the development of pterygium and the collagen family, including COL3A1 and COL4A1 regulated by miR-29b-3p and associated with PI3K-Akt signalling pathway, might serve roles in the pathogenesis of pterygium." (PMID 31341891, 2019). "FN1 and the collagen family, including COL1A1, COL3A1, and COL4A1, were the components of ECM, involved in the fibrotic type of fibrosis and might be a group of significant genes in pterygium." (PMID 31341891, 2019). "MiR-29b-3p and collagen family (COL4A1 and COL3A1) might be new treatment target in pterygium." (PMID 31341891, 2019).
Renal cyst (2 papers, 2025 to 2026). A fluid filled sac in the kidney. "While the primary focus was on identifying COL4A1 variations, the study also included one patient with TBM disease and bilateral renal cysts who was heterozygous for a likely pathogenic missense variant in COL4A5." (PMID 40565535, 2025).
sarcoma (2 papers, 2020 to 2021). A usually aggressive malignant neoplasm of the soft tissue or bone. "The Rb1 nullizygous sarcomas had a significantly lower number of tumors expressing COL18A1, COL4A1, and PLOD2." (PMID 33708626, 2021). "In general, murine sarcomas with Rb1 nullizygosity were associated with the undifferentiated morphology, except for one case identified as aRMS which also showed lower expression of COL18A1, COL4A1, and PLOD2 compared to Rb1 wildtype sarcomas (p = 0.0035, 0.04, and 0.08, respectively)." (PMID 33708626, 2021).
Seizure (2 papers, 2019 to 2024). A seizure is an intermittent abnormality of nervous system physiology characterized by a transient occurrence of signs and/or symptoms due to abnormal excessive or synchronous neuronal activity in the brain. "Seizures are very commonly reported in COL4A1 spectrum disorders." (PMID 39310498, 2024).
Strabismus (2 papers, 2020 to 2021). A misalignment of the eyes so that the visual axes deviate from bifoveal fixation. "The rare variants in OPA1 and COL4A1 were inherited from the father who had strabismus as a child, suffered from a traumatic macular haemorrhage in the left eye as an adolescent and went through cataract surgery in adulthood." (PMID 32040484, 2020). "As a result, we found three genes (ARID1B, ARNT2, COL4A1) intersected with the HPO strabismus gene list." (PMID 33435129, 2021).
uterine fibroids (2 papers, 2013 to 2022). "In the present study, the gene expressions of COL4A1, COL4A2 and COL6A3 were found to be increased in uterine leiomyomas." (PMID 23818951, 2013).
vesicoureteral reflux (2 papers, 2024 to 2025). Abnormal flow of urine from the urinary bladder back into the ureters. "Former three genes are transcription factor genes, participate general cell function, while the COL4A1/2 usually related to many genetic disorders, such as kidney abnormalities, and mutation on COL4A1 related to vesicoureteral reflux (VUR)." (PMID 40034749, 2025).
viral infection (2 papers, 2023 to 2024). "COL4A1 and GEM are genes involved in viral infection, while NRP1, which encodes neuropilin 1 (Nrp1), serves as an HTLV-1 receptor on target cells but has no reported function on HTLV-1-infected cells." (PMID 37375521, 2023).
abdominal aortic aneurysm (1 paper, 2021). Enlargement and ballooning of the vessel that supplies arterial blood to the abdomen, pelvis and legs. "In support of our hypothesis, we recently observed that genetic reduction of Col4a1/a2 in mice resulted in VSMC de-differentiation and accelerated development of abdominal aortic aneurysms, a condition which diabetic patients is partly protected against." (PMID 34496837, 2021).
Acidosis (1 paper, 2022). Abnormal acid accumulation or depletion of base. "Additionally, the top seven nodes of the “Acidosis” network were present among the top ten nodes of “Acidosis and Bone metastasis”: COL1A1, COL3A1, COL4A1, COL4A2, ITGB3, THBS2, and ITGA11." (PMID 35159353, 2022).
Aicardi–Goutières syndrome (1 paper, 2020). "Of these, 33 had Aicardi–Goutières syndrome, 6 had OCLN-related pseudo-TORCH syndrome and 3 had a COL4A1-related disease." (PMID 32895508, 2020).
aortic aneurysm (1 paper, 2023). A ruptured aneurysm located in the wall of the proximal portion of the descending aorta proceeding from the arch of the aorta. "Defects in the components of those pathways [Collagen Type IV Alpha 2 Chain (COL4A2), Collagen Type IV Alpha 1 Chain (COL4A1), Collagen Type VI Alpha 1 Chain (COL6A), Elastin (ELN)] were previously proposed to be associated with aortic aneurysm formation." (PMID 36922793, 2023).
Atrophy (1 paper, 2022). Any weakening or degeneration, especially through lack of use. "A second category of atrophy inducers consisted of RNAi for the extracellular matrix proteins cg25c and mfas, respectively homologous to collagen COL4A1 and to the collagen-binding protein TGFBI." (PMID 35501350, 2022).
autism (1 paper, 2023). Persistent deficits in social interaction and communication and interaction as well as a markedly restricted repertoire of activity and interest as well as repetitive patterns of behavior. "The patient's daughter, recently diagnosed with autism, underwent genetic testing, revealing a variant of uncertain significance (VUS) in the type IV collagen alpha 1 (COL4A1) gene." (PMID 38074064, 2023).
B-cell CLL (1 paper, 2016). "Similarly, activation of serine/threonine-protein kinases (Akt2 and Akt3) in combination with B-cell CLL/lymphoma (Bcl2), collagen (COL4A1), Src transforming protein (SHC1) lead to the activation of focal adhesion pathway." (PMID 27367858, 2016).
bladder tumors (1 paper, 2017). "The in vivo orthotopic experimental model of bladder tumors showed that intravesical treatment with siRNA targeting COL4A1 and COL13A1 inhibited the formation of the infiltrative pattern." (PMID 28415608, 2017). "Immunostaining analysis of orthotopic bladder tumors showed that both COL4A1 and COL13A1 were knocked down by intravesical treatment with COLs siRNA." (PMID 28415608, 2017). "IHC evaluation of human UCB tissues obtained from 97 patients revealed similar staining patterns for COL4A1 and COL13A1 as those in the orthotopic murine bladder tumors." (PMID 28415608, 2017). "There was almost no expression of COL4A1 in MGHU-3 and UM-UC-14 cells, whereas high expression was observed in the stromal area of the UM-UC-3-derived bladder tumor." (PMID 28415608, 2017).
cardiomyopathy (1 paper, 2023). A disease of the heart muscle or myocardium proper. "The hub genes COL4A2/COL4A1/SMAD3 may be potential research targets for cardiomyopathy-associated MI." (PMID 38001896, 2023). "COL4A2/COL4A1/SMAD3 were the hub genes in pericyte function involved in cardiomyopathy and AMI." (PMID 38001896, 2023).
cerebral infarction (1 paper, 2023). An ischemic condition of the brain, producing a persistent focal neurological deficit in the area of distribution of the cerebral arteries. "The first is the duplication of both the COL4A1 and (partial) COL4A2 genes in a affected individual (AD8) with multiple cerebral infarctions leading to neurological problems including movement disorders and speech problems." (PMID 36781956, 2023).
cerebral palsy (1 paper, 2024). A group of disorders affecting the development of movement and posture, often accompanied by disturbances of sensation, perception, cognition, and behavior. "COL4A1 gene mutations are close mimickers of Cerebral Palsy, hence a high index of suspicion should be exercised while approaching a child with spastic quadriplegia in order to promptly diagnose and manage such children for a better neurological outcome." (PMID 39310498, 2024). "Hence, more often than not COL4A1 mutations are known as ‘Cerebral Palsy’ mimics." (PMID 39310498, 2024).
childhood glaucoma (1 paper, 2025). "Variants in COL4A1 and PXDN, which are both basement membrane components, have been identified in patients with anterior segment dysgeneses associated with childhood glaucoma, although only the c.2159G>A p.(Gly720Asp) has been reported in more than one family." (PMID 41011222, 2025).
congenital diaphragmatic hernia (1 paper, 2016). A posterolateral defect of the diaphragm that allows passage of abdominal viscera into the thorax, leading to respiratory insufficiency and persistent pulmonary hypertension with high mortality. "The phenotype observed in Col4a1 and Col4a2 mutants is characterized by a block between the saccular and alveolar stages reminiscent of the severe abnormalities of premature newborns and children with congenital diaphragmatic hernia." (PMID 27412481, 2016).
corneal dystrophies (1 paper, 2020). "Other candidates genes include transforming growth factor beta-induced (TGFBI) or zinc-finger E-box binding homeobox 1 (ZEB1), involved in corneal dystrophies or COL4A1, COL4A2, COL4A2, and COL4A1, encoding collagen proteins responsible for the proper function of the cornea." (PMID 32879808, 2020).
COVID-19 (1 paper, 2022). A disease caused by infection with severe acute respiratory syndrome coronavirus 2. "MiRNAs that were downregulated in serum of COVID-19 patients mainly target genes promoting angiogenesis (e.g., VEGFA, ANGPT2, COL4A1, FGF2, ZEB1), apoptosis, autophagy, stress response (e.g., ATG12, ATG14, ATG2B, SOD2, TXNIP), and inflammation (e.g., CXCL9, CXCL10, IL1R1, TNF)." (PMID 36032130, 2022).
Crohn disease (1 paper, 2025). A gastrointestinal disorder characterized by chronic inflammation involving all layers of the intestinal wall, noncaseating granulomas affecting the intestinal wall and regional lymph nodes, and transmural fibrosis. "Similarly, COL4A1 has been identified as a potential diagnostic indicator in Crohn’s disease, highlighting its relevance in inflammatory conditions." (PMID 40087784, 2025).
dermatitis (1 paper, 2017). An inflammatory process affecting the skin. "This contrasts with the dermatitis model where both steroids had a small effect to reduce Col4a1, but over a shorter time course." (PMID 28131845, 2017).
diabetes insipidus (1 paper, 2016). A disorder characterized by excretion of large amounts of urine, accompanied by excessive thirst. "Metabolic cage studies revealed that Col4a1 mutations cause diabetes insipidus, because mice display the classical signs of reduced urine osmolality, polyuria and polydipsia." (PMID 26839400, 2016). "Col4a1 mutations also cause diabetes insipidus, whereby the tubular defects lead to polyuria associated with medullary atrophy and a subsequent reduction in the ability to upregulate aquaporin 2 and concentrate urine." (PMID 26839400, 2016). "Based on this, it is likely that these phenotypes, including the medullary atrophy, diabetes insipidus, polyuria and urine-concentrating defect, proteinuria and mild hypotension, can develop in at least a proportion of these individuals with COL4A1 mutations." (PMID 26839400, 2016). "Thus, inability to increase Aqp2 expression is in keeping with a generalised homeostatic failure of the distal nephron and, in Col4a1 mutant mice, leads to a failure to concentrate urine and diabetes insipidus." (PMID 26839400, 2016).
DiGeorge Syndrome (1 paper, 2022). "SROs with candidate genes were found in the established risk loci for other syndromes known to be associated with hypospadias, such as Silver–Russell Syndrome (PSMD13); 13q Deletion Syndrome (COL4A1); and 22q Deletion/Duplication Syndromes, which includes DiGeorge Syndrome (CRKL)." (PMID 35457073, 2022).
ductal carcinoma (1 paper, 2017). "and the experimental results showed that one of the most crucial genes, COL4A1, was the key gene that influence the proliferation and colony formation of the Invasive ductal carcinoma cell." (PMID 28938546, 2017).
Exotropia (1 paper, 2021). A form of strabismus with one or both eyes deviated outward. "In Family 11, an inherited missense variant in COL4A1 was found in two children (Family 11 II.1, II.2) and one parent (Family 11 I.2), both of whom have intermittent exotropia." (PMID 33435129, 2021).
factor VII deficiency (1 paper, 2021). A coagulation disorder characterized by the partial or complete absence of factor VII activity in the blood. "We collected data on: hemostatic genes (factor V deficiency, von Willebrand’s disease, factor VII deficiency), protrombothic genes (factor V Leiden, MTHFR mutation, protein C deficiency), collagen genes (COL4A1 and COL4A2 mutations), and X linked GATA1 gene mutation." (PMID 33920939, 2021).
fetal growth restriction (1 paper, 2021). A fetus that does not grow beyond the 10th percentile of conventionally accepted weight for gestational age. "In vivo, COL-4A1 increased blood pressure and elevated the risk of fetal growth restriction (FGR) which was induced by lipopolysaccharide (LPS) in the rat model." (PMID 34344927, 2021).
glomerulosclerosis (1 paper, 2025). A hardening of the kidney glomerulus caused by scarring of the blood vessels. "The attenuated progression of glomerulosclerosis, mesangial expansion, and fibrosis marker expression (e.g., Col4a1, Tgfb1) in p66Shc−/− mice highlights a direct role for this protein in modulating the structural remodeling associated with renal aging." (PMID 41303581, 2025).
IgA nephropathy (1 paper, 2023). "For example, IgA nephropathy (IgAN), which is one of the most prevalent chronic glomerular diseases, had significantly more matrisome proteins (Col4a1, Lamb1, Hspg2, Emilin, Fgg and Fbln) in diseased patients compared to healthy patients." (PMID 36769148, 2023).
inflammatory bowel disease (1 paper, 2025). A spectrum of small and large bowel inflammatory diseases of unknown etiology. "Two disease-related pathways — inflammatory bowel disease (cfa05321; GATA3, TLR4) and cancer pathways (cfa05222; COL4A1, E2F3, RARB) — were also enriched." (PMID 40764990, 2025).
Insulin resistance (1 paper, 2019). Increased resistance towards insulin, that is, diminished effectiveness of insulin in reducing blood glucose levels. "Rho family GTPase 3 (RND3), PARD6A, TLE2, FBLN2, COL4A1, and COL4A2 are novel biomarkers for the development of insulin resistance." (PMID 30678306, 2019).
keloid (1 paper, 2025). An irregularly shaped, elevated mark on the skin caused by deposits of excessive amounts of collagen during wound healing. "Among the genes enriched in the extracellular region pathway, 24 genes including COL1A1, COL1A2, and COL4A1 were significantly upregulated in keloid tissues." (PMID 41562114, 2025). "Isolated deep lesional fibroblasts display elevated expressions of collagen type I alpha 1 chain (COL1A1), consistent with our findings where COL1A1, COL1A2, COL4A1, and COL5A1 were prominently upregulated in keloid tissues." (PMID 41562114, 2025).
laryngeal carcinoma (1 paper, 2024). Carcinoma that arises from the laryngeal epithelium. "To validate whether hub genes contribute to HNC development, we selected one of the genes, that is, COL4A1, and examined its effects on cell proliferation, migration, invasion, and apoptosis in human laryngeal cancer cells." (PMID 38478802, 2024).
Lissencephaly (1 paper, 2011). A spectrum of malformations of cortical development caused by insufficient neuronal migration that subsumes the terms agyria, pachygyria and subcortical band heterotopia. "Based on our observations in the retina, we predicted that Col4a1+/Δex40 mice might also show pial basement membrane disruptions and cerebral cortical lamination defects that model cobblestone lissencephaly seen in MEB/WWS." (PMID 21625620, 2011).
lung diseases (1 paper, 2024). "Since the BM and its component collagen IV probably play a major role in the pathophysiological development of lung diseases in newborn infants it is important to define COL4A1 expression in different lung conditions." (PMID 38331745, 2024). "Interestingly, many patients in our study (Group 2) had low extracellular COL4A1 expression without association with lung maturation level or type of lung disease." (PMID 38331745, 2024).
melasma (1 paper, 2022). "TheWNT3A, EDN3, ESR2, PTG2, MMP1, and SOD2 genes were up-regulated, whereas the COL4A1, CSF2, DKK3, COL7A1, TIMP4, CCL2, and CDH11 genes were down-regulated in melasma skin fibroblasts when compared to the ones from adjacent healthy skin." (PMID 35840442, 2022). "There was an increase in MMP1 gene expression and a decrease in collagen IV, VII (COL4A1, COL7A1), and TIMP4 expression in fibroblasts isolated from melasma skin." (PMID 35840442, 2022).
mesothelioma (1 paper, 2021). A usually malignant and aggressive neoplasm of the mesothelium which is often associated with exposure to asbestos. "Also, the prognosis of mesothelioma is associated with COL3A1, COL4A1, and COL15A1." (PMID 34691289, 2021).